SDR42E1 (short chain dehydrogenase/reductase family 42E, member 1)
Synonyms: HSPC105
Tractability: Small molecule: it belongs to a druggable protein family. Antibody: UniProt predicts a signal peptide or a membrane-spanning region. PROTAC: ubiquitination databases record sites on it.
Gene: Protein-coding gene on chromosome 16 (81,988,855 to 82,011,482, reverse strand). Ensembl gene ENSG00000184860.
Subcellular location: Membrane
Gene Ontology:
Molecular function: oxidoreductase activity, acting on the CH-OH group of donors, NAD or NADP as acceptor
Biological process: steroid biosynthetic process
Cellular component: membrane
Genetic constraint (gnomAD): Loss-of-function variants: 12 observed, 10.09 expected, observed/expected ratio (o/e) 1.19, 90% interval 0.76 to 1.8. The upper end of that interval is the gene's LOEUF score, 1.8, which puts it in group 6 of 6, group 1 being the genes least tolerant of losing a copy. Missense variants: 596 observed, 503.28 expected, observed/expected ratio (o/e) 1.18, 90% interval 1.11 to 1.27. Synonymous variants: 231 observed, 199.37 expected, observed/expected ratio (o/e) 1.16, 90% interval 1.04 to 1.29.
Homologues: Orthologues: chimpanzee SDR42E1 (99% identical), macaque SDR42E1 (96% identical), dog SDR42E1 (89% identical), pig SDR42E1 (85% identical), guinea pig SDR42E1 (83% identical), rat Sdr42e1 (81% identical), mouse Sdr42e1 (80% identical), rabbit SDR42E1 (77% identical), zebrafish sdr42e1 (65% identical), tropical clawed frog sdr42e1 (59% identical), Caenorhabditis elegans hsd-2 (25% identical), Caenorhabditis elegans hsd-3 (25% identical). Paralogues in human: SDR42E2 (47% identical), HSD3B2 (29% identical), NSDHL (29% identical), HSD3B1 (28% identical), HSD3B7 (25% identical), GALE (21% identical), TGDS (20% identical), UXS1 (20% identical), GMDS (16% identical), GFUS (14% identical).
Diseases named in the same sentence as SDR42E1 in open-access papers:
SDR42E1 is named in the same sentence as 10 diseases in open-access papers, as found by Europe PMC text mining. Sharing a sentence is not in itself a finding about the gene and the disease. The quoted sentences say what the papers report.
breast carcinoma (1 paper, 2021). "We evaluated breast cancer single-cell RNA-seq data (n = 6 TNBC) and found that the SDR42E1 expression in our diagnostic biopsy samples is likely of epithelial cell origin while the TMEM176A/B expression is likely of stromal origin." (PMID 34922619, 2021).
colorectal cancer (1 paper, 2025). A primary or metastatic malignant neoplasm that affects the colon or rectum. "In alignment with the Hanahan and Weinberg framework, functional enrichment analysis indicates that SDR42E1 disruption intersects multiple oncogenic hallmarks, particularly those related to colorectal cancer progression and chemotherapy response." (PMID 40756515, 2025).
trisomy 21 (1 paper, 2024). A chromosomal disorder consisting of the presence of an extra chromosome 21. "The SDR42E1 gene expressed in two ToF studies and in one Trisomy 21/CHD study plays a crucial role in vitamin D biosynthesis, with variations in this gene linked to fragile cornea syndrome." (PMID 39596121, 2024).
vitamin D deficiency (1 paper, 2025). A nutritional condition produced by a deficiency of VITAMIN D in the diet, insufficient production of vitamin D in the skin, inadequate absorption of vitamin D from the diet, or abnormal conversion of vitamin D to its bioactive metabolites. "The findings advance our understanding of the molecular mechanisms underpinning vitamin D deficiency and highlight SDR42E1 as a potential molecular target." (PMID 40756515, 2025). "The largest genome-wide association study (GWAS) on vitamin D deficiency, identified a nonsense variant (rs11542462) on chromosome 16q23 that replaces glutamine with a termination codon at position 30 (p.Q30*), producing a truncated, non-functional SDR42E1 enzyme." (PMID 40756515, 2025).
cancer (3 papers, 2021 to 2025). A tumor composed of atypical neoplastic, often pleomorphic cells that invade other tissues. "ALDOA, a glycolytic enzyme implicated in cancer, may link SDR42E1 to glucose metabolism and vitamin D regulation." (PMID 40756515, 2025). "Collectively, these findings highlight SDR42E1 as a potential regulator of tumor biology and promising therapeutic target for improving cancer outcomes." (PMID 40756515, 2025). "Overall, our study elucidates valuable insights into the role of SDR42E1 in vitamin D metabolism and sterol processing, as well as its broader implications in cancer-related pathways." (PMID 40756515, 2025).
SDR42E1 also shares sentences with these, for which no sentence is quoted: tumor (3 papers); gastric cancer (1); hypoplastic left heart syndrome (1); Tetralogy of Fallot (1); uterine cancer (1).